RAC1 (Rac family small GTPase 1)
Diseases named in the same sentence as RAC1 in open-access papers (continued):
Sharing a sentence is not in itself a finding about the gene and the disease.
melanoma (continued). "The obtained results suggest that Rac1 is involved in the higher migration and cell spreading linked to KCTD5 depletion in melanoma cells, such as a constitutively active Rac1 construct enhanced both cellular responses in control, but not in B16-F10kctd5-/- cells." (PMID 33053687, 2020). "The second group comprised of serine/threonine-protein phosphatase 6 catalytic subunit (PPP6C), DEAD-box helicase 3 X-linked (DDX3X), phosphatase and tension homology (PTEN), and ras-related C3 botulinum toxin substrate 1 (RAC1) genes, which showed mutations in 5 to 9% melanoma tissues." (PMID 33256110, 2020). "P29S mutation in the highly conserved switch I domain of Rac1 is a fast-cycling mutation that decreases GTPase activity and increases interaction with downstream effector proteins, thereby promoting the proliferation and migration of melanoma." (PMID 32392742, 2020). "Importantly, the RAC1 P29S mutation was more frequent in melanomas that were wild type for both NRAS and BRAF." (PMID 31027363, 2019). "Following these clinical studies, several other investigators have confirmed that the RAC1 P29S hotspot mutation in melanoma may be an important predictor for vemurafenib and dabrafenib resistance in patients." (PMID 31027363, 2019). "Although the RAC1 P29S mutation is oncogenic and biochemically active, its clinical relevance in melanoma remains unclear." (PMID 31027363, 2019). "Finally, RAC1 was found to be recurrently mutated at the same position (RAC1 P29S) in melanoma samples in three independent studies with a mutation rate of 5%." (PMID 30987166, 2019). "Other oncogenes, RAC1 in particular, are associated with an increased risk of melanoma." (PMID 31636809, 2019). "We estimate that, in the US alone, the previously discussed RAC1:P29S mutation might be present in 628 new patients carrying the HLA-A*02:01 allele each year (in 556 melanoma patients and in 72 lung small cell, head & neck or uterine carcinomas patients)." (PMID 31775766, 2019). "However, deletion of Prex1, encoding an upstream activator of RAC1, has been reported to suppress migration and metastasis in a melanoma model." (PMID 31257073, 2019). "Interestingly, tumor associated activating mutations in Rac1 and Rac2 have been identified in melanoma, sarcoma, and tumors of the head and neck, breast, and brain." (PMID 30609754, 2019). "Considering the relationship between the functional PD1-PD-L1 axis and the efficacy of immunotherapy drugs, PD-L1 positive tumors (melanomas) expressing oncogenic RAC1 P29S hotspot mutation may be a suitable situation to test immunotherapy drugs." (PMID 31027363, 2019). "RAC1 has been associated with the expression of PD-L1 in melanomas carrying RAC1 P29 mutations." (PMID 31027363, 2019). "The RAC1 P29S mutation is present in around 4% of melanomas." (PMID 31257073, 2019). "Interestingly, the RAC1 GTPase activating mutation (P29S) is the third most frequently occurring mutation in sun-exposed melanoma (~9%)." (PMID 30460237, 2018). "Signaling cascades, such as the RAS/RAF/ERK1/2 pathway, the PI3K/AKT pathway, Ras-related C3 botulinum toxin substrate 1 (RAC1) and Nuclear factor kappa-light-chain-enhancer of activated B cells (NFκB)-associated pathway are involved in melanoma initiation and progression in vivo." (PMID 30544544, 2018). "Interestingly, Rac1/P29S was shown to be the third most recurrent mutation in melanomas, after the B-Raf/V600 and N-Ras/Q61 mutations, and it is considerably more frequent in samples that were wild-type for B-Raf or N-Ras." (PMID 30544828, 2018). "In simple logistic regression, RAC1 rs10951982 (odds ratio (OR) 8.98, 95% confidence interval (CI): 5.08 to 16.44; p < 0.001) reached universal significance (p = 0.002) and the minor alleles were associated with increased risk of melanoma." (PMID 29342889, 2018). "A very recent study confirmed the frequent occurrence of PPP6C and RAC1 mutations in melanoma." (PMID 29156643, 2017).
melanoma (continued). "Since these differences could be due at least in part to mutated hyper-activated Rac1, we sequenced Rac1 mRNA in our melanoma cells." (PMID 26248315, 2015). "A survey of mutant genes in melanoma revealed a high frequency of Rac1 mutations; Rac1 acts to modify the cytoskeleton and loss could potentially change Hippo pathway regulation." (PMID 23720711, 2013). "Most recently, activating Rac1 mutations were found in various forms of cancer, including melanoma." (PMID 23874639, 2013). "Recently, Lodde and collaborators showed the largest group of RAC1-mutated melanoma patients reported so far (n = 64), with RAC1 mutation identified in approximately 2% of samples; the most frequent was PS9S; 84% were cutaneous melanoma, and 14% of unknown primary." (PMID 40872623, 2025). "Furthermore, the activities of RAC1 have been reported to involve different stages of oncogenesis, such as initiation, progression, invasion, and metastasis, even it was ranked as the third most frequently occurring mutation in melanoma induced by UV." (PMID 36452505, 2022). "Moreover, Rac1 gain-of-function mutations have been identified in recent years, such as the two somatic mutations Rac1P29S and Rac1A159V, respectively detected in melanoma and in head-and-neck cancers, and occasionally observed in colon, thyroid, and lung cancers." (PMID 35740379, 2022). "Furthermore, activities of RAC1 have been reported involving different stages of oncogenesis such as initiation, progression, invasion, and metastasis, and it was even ranked as the third most frequently occurring mutation in melanoma induced by UV." (PMID 36387162, 2022). "Importantly, 1A-116 is able to interfere with Rac1 P29S mutant activity, and this may provide an interesting therapeutic strategy for melanoma patients with a particular mutation profile." (PMID 32351958, 2020). "Functionally, mutated RAC1 may increase the proliferation of melanoma cells." (PMID 30987166, 2019). "We have investigated the impact of signaling by RAC1, an oncogene which is mutationally activated in 4% of melanomas and may be activated by alterations in upstream regulators in a larger fraction, showing that RAC1P29S promotes the initiation of melanoma driven by mutant BRAF or NF1 loss." (PMID 31257073, 2019). "However, a known Rac1 mutation—RAC1P29S—is the third most common mutation associated with melanoma." (PMID 30791562, 2019). "In addition, RAC1 mutations have been observed in 9.2% of sun-exposed melanomas: these mutations were more frequent in melanomas that were wild-type for both NRAS and BRAF (12.5% of melanomas with wild-type BRAF and NRAS had the mutation compared to 6.2% of melanomas with mutant BRAF or NRAS)." (PMID 29156643, 2017). "RAC1 effectors include various protein kinases, offering a target for pharmacological inhibition, which may be of therapeutic value in the treatment of melanomas harboring the RAC1P29S mutations, although experimental evidence in support of this hypothesis is necessary." (PMID 25344914, 2014). "Likewise, the small Rho GTPase Rac1 is a factor known to be required for self-renewal and expansion of postmigratory neural crest stem cells, and recently, an activating mutation in RAC1 has been identified to drive melanoma formation." (PMID 24597924, 2014). "In melanoma, the hyperactive RAC1 mutant, Rac1P29S, was recently shown to drive extended lamellipodia, which then empower cell proliferation through sequestration and localized inhibition of the merlin tumor suppressor." (PMID 42282028, 2026). "To investigate the functional impact of the P29S mutation on RAC1 activity in melanoma cells and to validate our biochemical findings in HEK-293T cells, we used IGR1 human melanoma cells, which express the RAC1P29S mutant endogenously." (PMID 41034404, 2025). "Although RAC1 is a critical therapeutic target in melanoma, its undruggable nature poses a significant challenge for targeting RAC1P29S." (PMID 41034404, 2025).
melanoma (continued). "We find that Rac1-driven melanomas manifest pleiotropic resistance mechanisms including (i) reduced dependence on BRAF/MEK, (ii) activation of alternative MAPK pathways utilizing Jun kinase and p38 MAP kinase, and (iii) a partial reliance on YAP/TAZ signaling." (PMID 41109929, 2025). "Like A375 melanoma cells expressing Vav1 or Rac1 P29S, the BRAFi-resistance phenotype of VRPP1-3 cells was blunted by the group I PAK inhibitor G-5555, confirming that group I PAKs can also contribute to spontaneous Rac1-driven BRAFi resistance." (PMID 41109929, 2025). "By destabilizing Rac family small GTPase 1 (RAC1) mRNA and suppressing metastasis, this interaction spotlights a novel strategy to combat the aggressive spread of melanoma, a cancer notorious for its invasive properties." (PMID 40271197, 2025). "Collectively, these data implicate RAC1 signaling in the resistance to MAPK-targeted therapy and support the reported role for activating RAC1P29S mutations in melanoma resistance to vemurafenib." (PMID 39636745, 2025). "Intriguingly, melanoma-associated RAC1-activating mutations seem to be mutually exclusive with PTEN loss, suggesting a scenario whereby loss of PTEN drives wild-type RAC1 activation via PREX2 activation." (PMID 39636745, 2025). "Until now, preclinical Rac inhibitors all demonstrated limited activities in RAC1-driven melanoma models in vivo." (PMID 39941730, 2025). "Analysis of TCGA Pan-Cancer Atlas dataset revealed a 9-fold and 4-fold enrichment of RAC1 mutations in melanoma (6.53%, n = 29/444) and HNSCC (2.94%, n = 13/510), when compared to the average pan-cancer RAC1 mutation rate of 0.728% (76/10433 cases)." (PMID 39941730, 2025). "The corollary of these findings is that PTEN loss would upregulate the GEF activity of PREX2 and, consequently, stimulate RAC1 function, potentially rendering targeting of PREX2 in the context of PTEN-deficient melanoma a rational approach." (PMID 39636745, 2025). "Ras-related C3 botulinum toxin substrate 1(RAC-1)-mutant melanomas displayed a greater PD-L1 expression, resulting in T-cell inactivation and the absence of immune detection." (PMID 40872475, 2025). "In previous studies, SRF has been shown to be activated by RAC1 P29S, initiating transcriptional programs that promote malignant progression of melanoma." (PMID 40959096, 2025). "We examined the rates of RAC1 amplification in several independent metastatic melanoma cohorts, as melanoma is known to be highly metastatic in nature." (PMID 39941730, 2025). "We confirmed a critical role for Rac1 in BRAFi resistance conferred by Vav1 and identified complex, pleiotropic mechanisms by which Rac1 and Rac1 GEFs can drive BRAFi resistance in melanoma." (PMID 41109929, 2025). "Here we sought to elucidate the mechanisms by which DBL family GEFs and Rac1 can drive BRAFi resistance and identify additional strategies for targeting Rac1-driven drug-resistant melanomas." (PMID 41109929, 2025). "In this complex, RAC1 mRNA translation is inhibited, and the low level of RAC1 protein limits melanoma metastasis." (PMID 39972489, 2025). "Selective PI3K inhibitors were able to prevent melanoma cell proliferation and migration driven by mutant Rac1." (PMID 38791951, 2024). "The best described Rac1 effectors are the PAKs as they showed the sensibilization of the Rac1 P29S mutant melanoma cell lines and xenografts." (PMID 38791951, 2024). "Another Rac1-regulated pathway in melanoma is PI3K-AKT, which also contributes to EMT and migration." (PMID 38791951, 2024). "For example, RAC1P29S melanoma harbored increased PD-L1 expression compared to RAC1 wild type or other RAC1 mutants." (PMID 39507618, 2024). "WRC is activated by EphA2 through RAC1; therefore, WRC is an important intersection in melanoma migration from oncogenic BRAF signaling and Pten loss-mediated signaling." (PMID 38233537, 2024). "For instance, the ectopic overexpression of Rac1 in mouse melanoma cells has been shown to increase the invasiveness." (PMID 38791951, 2024).
melanoma (continued). "The oncogene RAC1 in melanoma is a member of the Rho family of GTPases14,15, and activates the WAVE regulatory complex (WRC)." (PMID 38233537, 2024). "In mouse models, deletion of the PREX1 gene leads to reduced Rac1 activity and metastasis in melanoma." (PMID 38191532, 2024). "Five of nine identified ER stress-related genes, CEBPB, TYR, SLC2A1, NOTCH3 and RAC1, have been reported to engage in melanoma malignant behavior regulation." (PMID 37217516, 2023). "Still, our study only included the validation of RAC1 in melanoma cell proliferation, apoptosis and migration." (PMID 37217516, 2023). "The forest plot shows that IFNAR2, LBP, CXCL9, and TLR2 are the protective genes for melanoma, while RAC1 and MAPK10 are the risk genes for melanoma." (PMID 37666853, 2023). "Wogonin inhibits melanoma cell migration, adhesion, invasion, and actin remodeling in vitro by suppressing the expression of matrix metalloproteinase-2 and Rac1." (PMID 36661523, 2023). "Due to its importance in proliferation, metastasis and drug resistance, Rac1 is an important therapeutic target in melanoma, but so far is considered undruggable, which makes targeting Rac1P29S in melanoma a challenge." (PMID 36875127, 2023). "In our study, we validated that the suppression of the RAC1 expression indeed attenuated the proliferation and migration as well as augmented the apoptosis of melanoma cells, which was consistent with the conclusions reported in other studies." (PMID 37217516, 2023). "Alternatively, the expression of the immune checkpoint, PD-1/PD-L1 and CTLA4, was augmented in the melanoma cells with the knockdown of RAC1." (PMID 37217516, 2023). "As expected, the RNA levels of CTLA1, PD-1/PD-L1 were significantly augmented in RAC1 knockdown melanoma cells by qRT-PCR analyses." (PMID 37217516, 2023). "In the current study, the expressions of Pyk2 and RAC1 in melanoma cells were significantly affected by the alteration of PCDH9." (PMID 36387162, 2022). "In our study, we found a new mechanism that the circZNF609 can go through the circZNF609/FMRP/RAC1 axis to suppress the melanoma metastasis." (PMID 35534866, 2022). "Nonetheless, the outcome of the dose-response experiments was consistent with our prior observation that RAC1-knockdown sensitized a subset of cutaneous melanomas to BRAFi." (PMID 36271142, 2022). "A phenotypic rescue experiment further confirmed that circZNF609 plays a role in regulating the metastasis of melanoma through RAC1." (PMID 35534866, 2022). "Conversely, Rac1 is often overexpressed and hyperactivated in cancers, notably in breast, colon, skin (melanoma), liver and lung cancers." (PMID 35740379, 2022). "Mechanistically, circZNF609 promoted the binding of FMRP protein and RAC1 mRNA, thereby enhancing the inhibitory effect of FMRP protein on the stability of RAC1 mRNA and ultimately inhibiting melanoma metastasis." (PMID 35534866, 2022). "RAC1 helps de-differentiated melanomas grow and/or withstand BRAFi and helps maintain the de-differentiated state." (PMID 36271142, 2022). "In conclusion, PCDH9, which is regulated by the circ 0084043-miR-134-5p axis, can suppress malignant biological behavior in melanoma and influence the expression levels of Pyk2, RAC1, Cyclin D1, MMP2, and MMP9." (PMID 36387162, 2022). "As a result, the WAVE2 functions to link intracellular Rac1/ROS signaling to B16 melanoma cell invasive migration is blocked by dieckol." (PMID 35736190, 2022). "PAK1/2 were overactivated in BRAFi- and MAPKi-resistant melanomas in vitro, most likely due to the increased expression levels of direct regulators (RAC1 and CDC42) and the PAK themselves." (PMID 35159327, 2022). "In vitro Transwell and 3D invasion assays demonstrated that silencing RAC1 functionally abolished the induction of melanoma migration and invasion elicited by circZNF609 depletion." (PMID 35534866, 2022).
melanoma (continued). "We also observed that RAC1 signaling opposes the proliferative effect of MITF because RAC1P29S suppressed the growth of differentiated melanomas." (PMID 36271142, 2022). "Regarding EGFR-mediated control of tensile Rac1 activity, ERK/MAPK signalling has been implicated to drive the overexpression and activation of the Rac-GEF in BRAF- and NRAS-mutant melanoma, as well as in KRAS- and EGFR- mutant lung cancer." (PMID 36224221, 2022). "As positive controls, we also expressed RAC1P29S in two BRAFi-sensitive melanomas (A375 and 451Lu) in which RAC1-knockdown did impact sensitivity to BRAFi." (PMID 36271142, 2022). "PD-L1 levels were higher in RAC1P29S melanoma patients than those in wild-type RAC1 patients, and in fact, RAC1P29S positively regulated PD-L1 protein levels in cultured cells; however, the mechanism was not studied." (PMID 35159327, 2022). "ROS levels, as well as B16 melanoma cell motility and invasion capacity, were shown to be connected to Rac1 activation and WAVE2 expression." (PMID 35736190, 2022). "Here, we show that RAC1 tends to be more important in de-differentiated melanomas for growth in standard conditions and/or during BRAFi." (PMID 36271142, 2022). "It has been found that the regulation of VIM and RAC1 mRNA translation by CSDE1 contributes to melanoma metastasis." (PMID 36354136, 2022). "Our results imply that de-differentiated melanomas would be vulnerable to compounds that inhibit RAC1." (PMID 36271142, 2022). "Our results suggested that the effect of PCDH9 on melanoma by RAC1 suppresses RAC1-dependent NADPH oxidase activity to decrease ROS generation and ROS-induced angiogenesis." (PMID 36452505, 2022). "Less frequent mutations in the NF1, RAC1, and PTEN genes were seen in the mut compared with wt patients from the 3-melanoma institution cohort." (PMID 34986841, 2022). "Mechanistically, we first discovered that circZNF609 directly binds FMRP and promotes the interaction of FMRP with RAC1 mRNA, thereby inhibiting RAC1 mRNA and protein levels and suppressing melanoma metastasis." (PMID 35534866, 2022). "Here, we show that wildtype RAC1 is a critical driver of growth and drug resistance, but only in a subset of melanomas with elevated markers of de-differentiation." (PMID 36271142, 2022). "One of these mutational networks presented in melanoma was the one containing MET besides CARD11, CBLB, PPP6C and RAC1." (PMID 34885093, 2021). "RAC1 mutant human melanoma cells are resistant to clinical inhibitors of BRAF but are uniquely sensitive to PAK inhibitors." (PMID 34827551, 2021). "The mutation in BAP1 was captured in the melanoma, as well as mutations in KMT2A (a known cancer driver mutation in melanoma) and TIAM1 (a gene involved in the RAC1 signaling pathway affecting cell shape and migration)." (PMID 35052351, 2021). "Another pathway regulated by RAC1 that plays an important role in melanoma is PI3K-AKT, which has also been described to play a role in EMT and migration." (PMID 34827551, 2021). "Research also revealed that clinostat-modeled SMG downregulated Rac1 expression in BL6-10 melanoma cells." (PMID 34068233, 2021). "Rac1 is known to enhance the elongated protruding movement of melanoma cells by promoting nuclear alterations through PAK1 and the tubulin cytoskeleton." (PMID 34201921, 2021). "The stimulation of NF-κB by Rac1 partly regulates the proliferation and invasion of the melanoma cell line FEMX." (PMID 34079763, 2021). "Most melanomas had oncogenic alterations such as RAC1 and AKT3 that stimulate the MAPK and PI3K pathways, reducing sensitivity to MAPK inhibitors." (PMID 34804979, 2021). "Rac1 Pro29 Ser also abrogates haptotaxis in fibroblasts and modulates invadopodia formation in melanoma cell lines." (PMID 34440759, 2021). "Immunohistochemistry for our 3D melanoma model showed that Cdc42, Rac1, and RhoA were constitutively expressed in the nuclei of melanoma cells of the untreated group, and NX-5 treatment decreased their expression." (PMID 34201921, 2021).